RAB27B (RAB27B, member RAS oncogene family)
Diseases named in the same sentence as RAB27B in open-access papers (continued):
Sharing a sentence is not in itself a finding about the gene and the disease.
myeloid malignancies (2 papers, 2023). "The findings in this work provide a potential mechanistic link between CBL/JAK2–mutated myeloid malignancies and activation of RAS signaling via upregulation of RAB27B." (PMID 37317963, 2023). "Future investigations are warranted to discover specific inhibitors against RAB27B for the treatment myeloid malignancies." (PMID 37317963, 2023). "Ren and colleagues have discovered a role of the CBL/JAK2/RAB27B/ZDHHC9 signaling axis in regulating NRAS trafficking to the plasma membrane for activation by palmitoylation in myeloid malignancies." (PMID 37317974, 2023). "To confirm our studies using mutant NRASQ61R, we examined the effect of RAB27B in NRASG12D, the most common mutant form of NRAS in human myeloid malignancies." (PMID 37317963, 2023). "In this study, we uncovered a previously unappreciated role for RAB27B in regulating NRAS palmitoylation, subcellular trafficking, and signaling in myeloid malignancies, in part via interacting with the palmitoyl acyltransferase ZDHHC9." (PMID 37317963, 2023). "The upregulation of RAB27B in JAK2V617F MPNs and its correlation with AML prognosis prompted us to investigate the potential role of RAB27B in myeloid malignancies." (PMID 37317963, 2023). "Hence, this work reveals what we believe to be new signaling dynamics that enhance our understanding of compartmentalized RAS signaling, suggesting RAB27B as a therapeutic target to abrogate oncogenic CBL/JAK2 and RAS-driven myeloid malignancies." (PMID 37317963, 2023). "Hence, we believe that this work uncovered a new signaling dynamic that enhances our understanding of compartmentalized RAS signaling, suggesting that targeting RAB27B may be therapeutically useful in oncogenic CBL/JAK2 and RAS driven myeloid malignancies." (PMID 37317963, 2023).
Obesity (2 papers, 2022 to 2024). Accumulation of substantial excess body fat. "Our data now suggest that allele T of rs12456731 leads to an increased expression of RAB27B in the gastric corpus and thereby increases the risk for different obesity-related traits and childhood BMI." (PMID 38406838, 2024).
osteosarcoma (2 papers, 2016 to 2020). A usually aggressive malignant bone-forming mesenchymal neoplasm, predominantly affecting adolescents and young adults. "Here, we revealed for the first time that miR-193a-3p and miR-193a-5p are also involved in the suppression of osteosarcoma metastasis through two newly identified target genes, namely Rab27B and SRR." (PMID 26913720, 2016). "In this study, we demonstrated that miR-193a-3p and miR-193a-5p suppress the metastasis of human osteosarcoma cells by repressing Rab27B and SRR expression, through suppressing the TGFβ, Myc/Max and ATF2/ATF3/ATF4 signaling pathways." (PMID 26913720, 2016). "To clarify the biological roles of Rab27B and SRR in osteosarcoma cells, we knocked down endogenous Rab27B and SRR expression using specific small interfering RNAs (siRNAs) in MG63.2 cells." (PMID 26913720, 2016). "Our present study showed for the first time that miR-193a-3p and miR-193a-5p can suppress human osteosarcoma cell metastasis by suppressing two novel targets, Rab27B and SRR, respectively." (PMID 26913720, 2016). "Hence, miR-193a-3p and miR-193a-5p negatively regulate osteosarcoma metastasis by targeting Rab27B and SRR, respectively." (PMID 26913720, 2016). "Our work suggested for the first time that miR-193a-3p-regulated Rab27B and miR-193a-5p-regulated SRR contribute to the invasion and metastasis of osteosarcoma." (PMID 26913720, 2016). "We next determined if Rab27B and SRR dysregulation was involved in the miR-193a-3p- and miR-193a-5p-induced migration and invasion of osteosarcoma cells." (PMID 26913720, 2016). "Taken together, these results suggested that Rab27B and SRR are direct and functional targets of miR-193a-3p and miR-193a-5p, respectively, and that they are involved in the miRNA-induced suppression of osteosarcoma cell migration and invasion." (PMID 26913720, 2016). "MiR-193a-3p and miR-193a-5p play important roles in osteosarcoma metastasis through down-regulation of the Rab27B and SRR genes and therefore may serve as useful biomarkers for the diagnosis of osteosarcoma and as potential candidates for the treatment of metastatic osteosarcoma." (PMID 26913720, 2016).
renal cell carcinoma (2 papers, 2020 to 2024). "The mRNA expression levels of RAB27A and RAB27B mRNA were evaluated in eight renal cell carcinoma (RCC) cell lines." (PMID 38685086, 2024).
allergic disease (1 paper, 2007). An immune response that occurs following re-exposure to an innocuous antigen, and that requires the presence of existing antibodies against that antigen. "The identification of severely reduced mast cell responses in vivo in the Rab27b KO mouse is the first report that Rab27b contributes to allergic responses in mammals and suggests that Rab27b may be a future drug target for allergic diseases, such as asthma." (PMID 17587407, 2007).
Anxiety (1 paper, 2026). Intense feelings of nervousness, tension, or panic often arise in response to interpersonal stresses. "Multi-omic integration identified RAB27B as a driver of the anxiety-related pathway, implicating synaptic vesicle trafficking and neuroimmune regulation, while GPNMB and KLHL7 supported anxiety-independent pathways involving musculoskeletal remodeling and peripheral inflammation." (PMID 41796324, 2026).
autism spectrum disorder (1 paper, 2019). A spectrum of developmental disorders that includes autism, and Asperger syndrome. "The SYTL4 gene is known to directly interact with several members of the RAB family of genes, such as, RAB27A, RAB27B, RAB8A, and RAB3A which are known autism spectrum disorder genes." (PMID 31323913, 2019).
brain cancer (1 paper, 2020). A primary or metastatic malignant neoplasm affecting the brain. "In conclusion, we found that Rab27b and EREG are co-upregulated in highly aggressive brain cancer cells, and their expression is further increased after IR treatment, leading to radioresistance in GBM." (PMID 33409495, 2020).
brain tumors (1 paper, 2020). "We then confirmed the increased protein levels of Rab27b and EREG in mouse brain tumors after IR treatment by IHC staining." (PMID 33409495, 2020).
chronic hepatitis B infection (1 paper, 2017). "Compared with that from normal humans and patients with chronic hepatitis B infection, RAB27B in sera from patients with HCC exhibited significantly increased levels (p = 0.673, p < 0.001, p < 0.001)." (PMID 28977851, 2017). "Compared with healthy controls and patients with chronic hepatitis B infection, serum RAB27B was significantly increased in patients with HCC." (PMID 28977851, 2017). "In summary, our study revealed that serum RAB27B expression was remarkably elevated in patients with HCC, compared to healthy controls and patients with chronic hepatitis B infection." (PMID 28977851, 2017). "Western blotting was carried out to evaluate the expression of RAB27B in serum samples from 154 patients with HCC, 40 healthy controls, and 31 patients with chronic hepatitis B infection." (PMID 28977851, 2017). "Moreover, in this study, we assessed the differential expression of RAB27B in the sera of patients with HCC, as well as in that of normal humans and patients with chronic hepatitis B infection, to elucidate its potential significance in early diagnosis of HCC." (PMID 28977851, 2017).
Cirrhosis (1 paper, 2025). A chronic disorder of the liver in which liver tissue becomes scarred and is partially replaced by regenerative nodules and fibrotic tissue resulting in loss of liver function. "In this study, Rab27a expression was upregulated in the livers of patients with cirrhosis and in BDL mice, and its expression tended to be greater than that of Rab27b." (PMID 39804962, 2025).
colitis (1 paper, 2022). Inflammation of the colon. "To our surprise, yet demonstrating specificity, we also found that Rab27a and Rab27b were dispensable within the IEC compartment during DSS-induced colitis despite high expression in IECs." (PMID 36214220, 2022). "We found that knocking out either Rab27a or Rab27b in the IECs did not affect DSS-induced colitis weight loss." (PMID 36214220, 2022). "Further, we have also ruled out a contribution by Rab27a-dependent, T cell–derived exosomes and Rab27b-dependent, hematopoietic derived exosomes in regulating gut inflammatory responses during DSS colitis." (PMID 36214220, 2022).
colon cancer (1 paper, 2024).
Griscelli syndrome (1 paper, 2007). Griscelli syndrome (GS) is characterized by silvery gray sheen of the hair and hypopigmentation of the skin which can be associated to neurological impairment (type 1), immunodeficiency (type 2) or be isolated (type 3). "The partial redundancy of the Rab27 isoforms was expected given our previous studies on the pathogenesis of Griscelli syndrome where we showed that transgenic heterologous expression of Rab27b in melanocytes could compensate for melanosome clustering and coat color dilution in Rab27a KO (ash) mice." (PMID 17587407, 2007).
hemorrhagic disease (1 paper, 2007). Spontaneous or near spontaneous bleeding caused by a defect in clotting mechanisms (blood coagulation disorders) or another abnormality causing a structural flaw in the blood vessels (hemostatic disorders). "We have shown that Rab27b KO and double Rab27a/Rab27b KO mice exhibit significant hemorrhagic disease." (PMID 17587407, 2007).
liver cancer (1 paper, 2017). An epithelial or non-epithelial malignant neoplasm that arises from the liver. "First, the correlation between serum RAB27B expression and survival, as well as TNM and Barcelona Clinic Liver Cancer stages, were evaluated in patients with HCC." (PMID 28977851, 2017).
lymphoma (1 paper, 2021). A malignant (clonal) proliferation of B- lymphocytes or T- lymphocytes which involves the lymph nodes, bone marrow and/or extranodal sites. "Under suppressed secretion of exosomes by reducing RAB27B expression using siRNA, the susceptibility of lymphoma cells to gemcitabine was partially restored." (PMID 33994542, 2021). "The suppression of RAB27B, which is involved in the secretion of exosomes, using a specific siRNA resulted in reduced exosome secretion and decreased survival of lymphoma cells." (PMID 33994542, 2021). "In addition, the survival of lymphoma cells was significantly decreased in co-culture with RAB27B knocked-down CAFs." (PMID 33994542, 2021).
metastasis (1 paper, 2017). The spread or migration of cancer cells from one part of the body (where they first appeared) to another. "Moreover, this study has also revealed a correlation between RAB27B and poor differentiation and lymph node metastasis in ER-positive breast cancer." (PMID 28784136, 2017).
myeloid leukemia (1 paper, 2023). A clonal proliferation of myeloid cells and their precursors in the bone marrow, peripheral blood, and spleen. "Rab27b deficiency in mice inhibits oncogenic NRAS-mediated signaling, HSPC growth, and myeloid leukemia development in vivo." (PMID 37317963, 2023). "Taken together, these data demonstrate that Rab27b deficiency abrogates oncogenic NRAS-mediated ERK signaling and myeloid leukemia development in vivo." (PMID 37317963, 2023). "In agreement, while Rab27b–/– mice display no obvious abnormalities, Rab27b deficiency significantly abrogated myeloid leukemia development conferred by oncogenic NRAS." (PMID 37317963, 2023).
papillary thyroid carcinoma (1 paper, 2016). "Rab27b has been reported to be widely expressed in secretory organs such as the pituitary gland, pancreas, and thyroid gland, and is up-regulated in papillary thyroid carcinoma." (PMID 27409639, 2016).
prostate carcinoma (1 paper, 2018). A carcinoma that arises from epithelial cells of the prostate gland. "Rab27A and Rab27B are frequently downregulated in advanced prostate cancer and are inversely correlated with prostate cancer outcomes." (PMID 30081925, 2018).
schizophrenia (1 paper, 2025). A major psychotic disorder characterized by abnormalities in the perception or expression of reality. "Furthermore, the DA population in schizophrenia had decreased expression of genes associated with the GO term ‘GTPase activity’, such as Ras-related protein Rab-27B (RAB27B), and ADP ribosylation factor (ARL17B)." (PMID 39397771, 2025).
Sjögren's syndrome (1 paper, 2017). "In addition, expression of several genes known to be dysregulated in Sjögren's syndrome: CTSS, MHC-II, MMP9, Rab proteins (Rab3D, Rab27A, and Rab27B), IL12α, IFN-γ, TNF-α, and aquaporin 5 (Aq5), and the cholinergic muscarinic M3 receptor (M3R) were quantitatively measured using qPCR." (PMID 28348600, 2017).
status epilepticus (1 paper, 2019). Status epilepticus is defined as a continuous seizure lasting more than 30 min, or two or more seizures without full recovery of consciousness between any of them. "Rab27a and Rab27b expression was also increased after status epilepticus in the ipsilateral CA3 subfield." (PMID 32009885, 2019).
Thrombocytopenia (1 paper, 2024). A reduction in the number of circulating thrombocytes. "Among the common DEPs in this pathway, CD41 (ITGA2B) and Rab27b (RAB27B) were selectively reduced in patients with WAS, likely reflecting thrombocytopenia." (PMID 39453496, 2024). "CD3E levels were found to be reduced in patients with SCID, and those of Rab27B and platelet-related proteins were low in patients with WAS, likely reflecting thrombocytopenia and T cell lymphopenia, respectively, in these two IEIs." (PMID 39453496, 2024).
ulcerative colitis (1 paper, 2022). An inflammatory bowel disease involving the mucosal surface of the large intestine and rectum. "Compared with the healthy control group, a significant increase in the number of Rab27A+ or Rab27B+ intestinal immune cells can be observed in the colonic mucosa of the active ulcerative colitis group." (PMID 35371265, 2022).
tumor (63 papers, 2010 to 2025). "Consistent with CSCs driving tumor initiation in progression, we found that RAB27B-deficient tumors show reduced growth." (PMID 37077938, 2023). "When analyzed with regard to clinicopathological parameters, RAB27B mRNA expression showed significant association with tumor stage." (PMID 36980570, 2023). "It was consistent that oncogenic miR-21 and miR-155 involved in the progression and invasion of GBM, and a set of their common key targets such as LHX6, DRD1, NEUROG1 and RAB27B were also associated with tumor progression." (PMID 29312626, 2017). "In comparison, other clinical items, such as gender, age, tumor size and location, histological type, and tumor differentiation, were barely associated with high Rab27b protein expression." (PMID 25580113, 2014). "Cox multifactor analysis and Kaplan-Meier method suggested that higher Rab27b protein expression (P = 0.041) and tumor differentiation (P = 0.001) were significantly associated with the overall survival of CRC patients." (PMID 25580113, 2014). "High nuclear staining for Rab27B was significantly related to tumor size, mitotic index, AFIP Miettinen risk classification, and tumor grade." (PMID 25382899, 2014). "In this regard, in tumor growth experiments, shRAB27B knockdown tumors exhibit decreased CD31 expression, a marker of angiogenesis, suggesting that RAB27B-depleted cells are deficient in providing paracrine proangiogenic signals needed to establish tumor vasculature." (PMID 37077938, 2023). "Thus, it is rational to propose that Rab27b plays important role in tumor development and is critically associated with tumor progression." (PMID 25580113, 2014). "Furthermore, RAB27B mRNA and protein expression is associated with lymph node metastasis and tumour grade in ER-positive tumours." (PMID 24931391, 2014). "Positive staining of Rab27B was significantly associated with tumor size (P = 0.006), mitotic index (P = 0.013), Armed Forces Institute of Pathology Miettinen risk classification (P = 0.002), and tumor grade (P = 0.021)." (PMID 25382899, 2014). "Thus, we propose that Rab27B is associated with tumor progression because of its function as a transport vesicle." (PMID 23217148, 2012). "We selected two genes for this validation experiment – Cyp24A1 from 20q13.2 region, amplification of which was significantly associated with lymph node metastasis and RAB27B from 18q22.2 region deletion of which was significantly associated with tumor grade in combined analyses." (PMID 22363777, 2012). "In addition, knockdown of Rab27A and Rab27B is associated with increased accumulation of tumor-suppressive miRNA within bladder cancer cells, suggesting the secretion of tumor-suppresive miRNA through exosomes may be critical for tumor progression." (PMID 30925917, 2019). "We, therefore, used CRISPR to reduce protein expression of Rab27a or Rab27b in both micrometastatic and primary tumor cells and measured EV release into their conditioned media." (PMID 40488669, 2025). "Rab27A and Rab27B contribute to tumor formation progression in many types of cancer through various mechanisms, including the secretion of small extracellular vesicles (sEVs)." (PMID 39596498, 2024). "Similar to established NSCLC cell lines, primary NSCLC CSC cultures expressed elevated RAB27B mRNA levels when compared with the bulk tumor cells from which they were isolated." (PMID 37077938, 2023). "In this context, we assessed the clinical value of 8 genes (RAB2B, RAB3B, RAB9A, RAB11B, RAB27A, RAB27B, STX1A, and VAMP7), which are implicated in sEVs biogenesis, as well as their association with overall and tumor-derived plasma sEVs levels." (PMID 36980570, 2023). "In the case of Rab27b, more research is needed to investigate the potential role of Rab27b overexpression in NDEs in the context of tumor growth and treatment." (PMID 37376417, 2023).